OR2Z1 (olfactory receptor family 2 subfamily Z member 1)
Description:
Odorant receptor.
Synonyms: OR2Z2; OR19-4
Tractability: Antibody: UniProt places it where antibodies can reach, with medium confidence; UniProt predicts a signal peptide or a membrane-spanning region; its Gene Ontology location is reachable by antibodies, with medium confidence.
Gene: Protein-coding gene on chromosome 19 (8,721,634 to 8,732,160, forward strand). Ensembl gene ENSG00000181733.
Subcellular location: Cell membrane
Pathways (Reactome):
Sensory Perception: Expression and translocation of olfactory receptors
Gene Ontology:
Molecular function: olfactory receptor activity; G protein-coupled receptor activity
Biological process: detection of chemical stimulus involved in sensory perception of smell; G protein-coupled receptor signaling pathway
Cellular component: plasma membrane; membrane
Genetic constraint (gnomAD): Loss-of-function variants: 0 observed, 0.71 expected, observed/expected ratio (o/e) 0, 90% interval 0 to 1.79. That is too few expected variants to judge how well the gene tolerates losing a copy. Missense variants: 449 observed, 425.69 expected, observed/expected ratio (o/e) 1.05, 90% interval 0.98 to 1.14. Synonymous variants: 188 observed, 171.18 expected, observed/expected ratio (o/e) 1.1, 90% interval 0.97 to 1.24.
Homologues: Orthologues: chimpanzee OR2Z1 (99% identical), dog OR2Z1 (86% identical), rabbit OR2Z1 (84% identical), pig OR2Z1 (81% identical), rat Olr1096 (74% identical). Paralogues in human: OR2V1 (53% identical), OR2T33 (51% identical), OR2T8 (51% identical), OR2T27 (51% identical), OR2T12 (51% identical), OR2T2 (50% identical), OR2T35 (50% identical), OR2M4 (50% identical), OR2V2 (50% identical), OR2M5 (48% identical), OR2T1 (48% identical), OR2T11 (48% identical), and 80 more.